IL2 (interleukin 2)
Diseases named in the same sentence as IL2 in open-access papers (continued):
Sharing a sentence is not in itself a finding about the gene and the disease.
liver failure (2 papers, 2017 to 2022). A liver disease characterized by the liver losing or has lost all of its function. "Univariate analysis revealed that the incidence of liver failure was remarkably associated with age, IL-2, γ-GT, TBIL, WBC, and anti-Sp100." (PMID 36159788, 2022). "In conclusion, patients with PBC liver failure might have a relatively immunosuppressed state, predominantly caused by lymphocytopenia, which was probably related to the intervention of IL-2 on CD4 cell differentiation." (PMID 36159788, 2022). "According to Kaplan-Meier analysis, the incidence of liver failure was markedly increased when IL-2 levels were ≤ below 0.54 pg/ml or TBIL ≥ 115.21 μmol/ml." (PMID 36159788, 2022). "This study also provides the first evidence for the predictive efficacy of serum IL-2 combined with TBIL in PBC patients with liver failure." (PMID 36159788, 2022). "Age, IL-2, ALB, γ-GT, ALP, TBIL, Hb, TBA, WBC, and PLT, as well as anti-Sp100, were found to be independent risk factors in PBC patients with liver failure." (PMID 36159788, 2022). "This study aimed to investigate the prognostic significance of serum IL-2 combined with total bilirubin (TBIL) in liver failure and cytokine changes during the disease." (PMID 36159788, 2022). "The outcomes demonstrated that serum IL-2 levels in patients with advanced PBC liver failure after liver transplantation were lower than in healthy controls." (PMID 36159788, 2022). "Our experiment found that the reduction of serum IL-2 levels in patients with advanced PBC liver failure will lead to a decrease in Th1 type cells (serum TNF-α level in the blood approaches the normal value)." (PMID 36159788, 2022). "Subgroup analysis of the incidence of liver failure based on the cut-off values of IL-2 and TBIL was divided into three groups." (PMID 36159788, 2022). "Patients with advanced PBC liver failure after liver transplantation exhibited a significant decrease in levels of serum IL-2 and a relatively immunosuppressed status." (PMID 36159788, 2022). "Conversely, when IL-2 level ≥ 0.54pg/ml or TBIL <115.21μmol/ml, the incidence of liver failure in patients decreased dramatically." (PMID 36159788, 2022). "Therefore, by collecting clinical indicators and cytokine detection in patients with PBC, this study explores the change of IL-2 levels in patients with PBC during liver failure and analyzes whether IL-2 in combination with TBIL improves the predictive capacity." (PMID 36159788, 2022). "Patients with decreased serum IL-2 levels and increased TBIL levels have a significantly higher incidence of liver failure and a worse prognosis." (PMID 36159788, 2022). "Our study, for the first time, demonstrated the prognostic significance of serum IL-2 combined with TBIL and is likely to be related to the expression of GM-CSF and G-CSF in liver failure in PBC patients." (PMID 36159788, 2022). "The levels of cytokines, such as IL-10, IL-2, IL-4, IL-6, IFN-γ, and GM-CSF in PBC patients who developed liver failure, were significantly reduced, and the difference in IL-2 between the two groups was statistically significant (P=0.028)." (PMID 36159788, 2022). "Moreover, multivariate analysis showed that age(P=0.023), IL-2(P=0.023), TBIL(P=0.001), and anti-SP100(P=0.001) were independent predictors of the development of liver failure." (PMID 36159788, 2022). "Therefore, treatment with JDHY granules improves liver function in an acute model of rat liver failure by downregulating TLR4 and IL-2 pathways." (PMID 28197212, 2017).
Löfgren's syndrome (2 papers, 2009 to 2020). "mRNA expression of IL-2 was increased in patients (p < 0.01) and non-Löfgren's patients expressed significantly higher levels of IFN-γ mRNA (p < 0.05) versus patients with Löfgren's syndrome." (PMID 19480659, 2009).
lymphedema (2 papers, 2022 to 2024). Excess fluid collection in tissues, causing swelling. "On the contrary, the constitutive increase of the Tregs using Il2/anti-Il2 antibody complexes protected from lymphedema development, significantly reducing edema, and was associated with a reduced inflammatory burden." (PMID 39737964, 2024). "The systemic expansion of Tregs by intraperitoneal injection with IL-2/anti-IL-2 monoclonal antibody complexes (IL2-c) was effective for lymphedema to the same degree as adoptive Treg transplantation." (PMID 35886961, 2022).
malignant fibrous histiocytoma (2 papers, 2021 to 2024). "One of these patients had complete radiological resolution on MRI of the cardiac recurrence of a malignant fibrous histiocytoma following treatment with high-dose chemotherapy followed by peripheral blood progenitor cell transplant and immunotherapy with interleukin-2 and 13-cis-retinoic acid." (PMID 39330026, 2024).
malignant pleural mesothelioma (2 papers, 2009 to 2022). A malignant neoplasm that arises from mesothelial cells in the pleura and shows a diffuse growth pattern. "Administration of interleukin-2 (IL-2) has shown some effects on malignant pleural mesothelioma (MPM) tumour regression." (PMID 19935800, 2009). "Therefore, we hypothesize that NFE2L3, a novel biomarker in malignant pleural mesothelioma, may promote the differentiation of Th2 cells through the IL-2/STAT5/NLRP3 signaling pathway in multiple cancers." (PMID 35664314, 2022).
mantle cell lymphoma (2 papers, 2023). Mantle cell lymphoma is a rare form of malignant non-Hodgkin lymphoma affecting B lymphocytes in the lymph nodes in a region called the ``mantle zone''. "The first study was conducted by Wilhelm and collaborators, where a low-dose of IL-2 in combination with pamidronate was tested, according to two different schedules, in 19 patients with relapsed/refractory low-grade NHL (FL, CLL, mantle cell lymphoma-MCL) and MM." (PMID 37426670, 2023).
medullary thyroid carcinoma (2 papers, 2020 to 2024). "For example, lanreotide has been explored in conjunction with IL-2 in the treatment of medullary thyroid carcinoma (MTC), with early evidence suggesting that it may have a role in the treatment of advanced MTC." (PMID 39272962, 2024). "On this light, we have previously demonstrated that lanreotide can increase the activity of IL-2-activated peripheral blood mononuclear cells against a cellular model of NET of the thyroid, the medullary thyroid carcinoma (MTC) TT cell line." (PMID 32766136, 2020).
memory impairment (2 papers, 2013 to 2025). "In the present study, short-term aversive memory impairment was associated with increased levels of pro-inflammatory cytokines and decrease of regulatory mediators, such as IL-2 and IL-10, in the hippocampus and frontal cortex of P. berghei-infected mice." (PMID 24180288, 2013).
monoclonal-gammopathies (2 papers, 2024 to 2025). "Classical SCLS is most often associated with monoclonal gammopathy, hematologic malignancies, or elevated pro-inflammatory cytokines such as interleukin-2 (IL-2) and tumor necrosis factor-alpha (TNF-α)." (PMID 41281016, 2025).
multidrug-resistant tuberculosis (2 papers, 2023 to 2024). A type of drug-resistant tuberculosis that is resistant to both rifampicin and isoniazid, the two most powerful anti-TB drugs. "Our and other studies have shown that IL2 plays an important role in anti-Mtb infection, significantly reducing the bacterial burden in the lungs of multidrug-resistant tuberculosis (MDR-TB)-infected hosts, resulting in milder pathology/lesions and improved treatment outcomes." (PMID 39575242, 2024). "Studies suggest that IL-2 may provide immunotherapy to treat multidrug-resistant tuberculosis (MDR-TB)." (PMID 37243045, 2023).
myasthenia (2 papers, 2017 to 2024). "Furthermore, IL-2/IL-2 mAb complex is found to expand the Treg cells in EAMG mice, and therefore suppress the autoreactive T and B cells, thereby relieving the myasthenia symptom of EAMG mice." (PMID 39318549, 2024). "In an EAMG mice model, IL-2 secreted by NKT could expand the Treg cells, and thus relieve the myasthenia symptom of mice." (PMID 39318549, 2024).
Mycoplasma infections (2 papers, 2025 to 2026). "Some studies note rising IL-2 levels during mycoplasma infection and SMPP onset." (PMID 41313182, 2026).
myeloid malignancies (2 papers, 2023 to 2024). "In this study, NK cells obtained from PBMCs of an HLA haploidentical related donor, after an overnight incubation with IL-2 were infused at escalating doses (dose ranging from 0.02 to 8.32 × 106/kg) in 21 high-risk myeloid malignancies." (PMID 38247827, 2024). "The NCT04024761 trial is studying cytokine-induced memory-like natural killer (CIML-NK) cells plus IL-2 which leads to activation and expansion of the NK cells in patients above 12 years with myeloid malignancies who relapsed or remain MRD positive after haploidentical HSCT." (PMID 36983151, 2023).
Myocardial fibrosis (2 papers, 2022 to 2023). "Myocardial fibrosis is strongly associated with adverse outcome across a range of cardiovascular conditions and further work is required to determine the association between myocardial fibrosis and outcome in patients receiving IL-2 therapy." (PMID 35741162, 2022). "Autopsy data also demonstrate that approximately 50% of patients go on to develop myocardial fibrosis following IL-2 therapy, and that the fibrotic process begins early post-therapy." (PMID 35741162, 2022).
myositis (2 papers, 2015 to 2016). "Increased colon width, inflammatory infiltration, myositis, periganglionitis, ganglionitis, pro-inflammatory cytokines (e.g., TNF-α, INF-γ, IL-2, IL-17, IL-6), and intestinal amastigote nests were more pronounced in high parasite load-bearing animals." (PMID 25889515, 2015).
Neonatal sepsis (2 papers, 2020 to 2022). Systemic inflammatory response to infection in newborn babies. "GNT treatment decreased LPS-induced elevation of TNF-α, IL-2, and IL-1β expression levels and increased LPS-induced elevation of IL-10 expression levels in the peritoneal fluid, indicating the anti-inflammatory effect of GNT in neonatal sepsis." (PMID 36162982, 2022). "However, to our knowledge, there are no studies investigating sex-dependent differences of IL-2, CCL5, or IL-17 in neonatal sepsis." (PMID 32373108, 2020).
neuroendocrine tumors (2 papers, 2013 to 2019). "Former analyses revealed an association between serum cytokine levels and a polymorphic variant upstream to the IL2 gene promoter (−330 T/G, rs2060762) assessed in MS and in neuroendocrine tumors." (PMID 24154763, 2013).
neurotoxicity (2 papers, 2016 to 2024). Toxicity that causes injury to the central or peripheral nervous system or damages its function. "At home, following discharge from the second week of IL-2 therapy, she had mild toxic encephalopathy manifested as agitation, which responded to lorazepam for 3 days, and she had prolonged pruritus that was treated with gabapentin, begun after her discharge from the second week of IL-2." (PMID 27144182, 2016).
non-alcoholic fatty liver disease (2 papers, 2021 to 2023). "The non-traditional cardiovascular risk factors that we studied were the following: hs-CRP, TG/HDL ratio, ApoA1, ApoB, ApoB/ApoA1 ratio, leptin, adiponectin, homocysteine, IL-2, IL-4, IL-6, IL-10, IL-17A, TNF-α and INF-γ, and non-alcoholic fatty liver disease (NAFLD)." (PMID 37892418, 2023).
oral cavity cancer (2 papers, 2019). A primary or metastatic malignant neoplasm involving the oral cavity. "Moreover, another SNP in the inflammatory gene IL2 rs2069762 G variant was associated with a lower risk of oral cavity cancer (GG p = 0.039, OR = 0.300 (0.096–0.940))." (PMID 30959967, 2019).
otitis media with effusion (2 papers, 2025). Otitis media associated with accumulation of fluid in the middle ear. "The analysis of cytokine levels in adults with OME, including IL-2, IL-4, IL-5, IL-10, IL-12, and interferon (IFN)-gamma, reveals distinct patterns associated with otitis media with effusion (OME) and allergic conditions." (PMID 40497981, 2025). "The levels of IL-2, IL-6, IgE, and NO in MEE were significantly higher than those in peripheral blood in the experimental group (p < 0.01), suggesting that the increase in NO levels is involved in the pathogenesis of otitis media with effusion." (PMID 40227356, 2025).
ovarian hyperstimulation syndrome (2 papers, 2014 to 2021). A complication of ovulation induction in infertility treatment. "Increased synthesis of IL-2 by mural granulosa cells obtained from women with ovarian hyperstimulation syndrome has also been reported, but the significance of IL-2 in the ovarian follicle remains to be determined." (PMID 33616080, 2021).
paracoccidioidomycosis (2 papers, 2021 to 2022). A systemic fungal infection caused by Paracoccidioides brasiliensis that is most often seen in immunocompromised patients. "Mild or moderate chronic forms of paracoccidioidomycosis are now believed to occur in the context of Th17/Th22 lymphocytes and a mixture of cytokines IL-17 and IL-22 (high levels), IFN-γ, TNF-α, IL-2 and IL-10 and IL-4 (variable levels) and with high levels of IgG1 antibodies." (PMID 33668671, 2021).
Peri-Implantitis (2 papers, 2014 to 2018). An inflammatory process with loss of supporting bone in the tissues surrounding functioning DENTAL IMPLANTS. "This study evaluated the presence of cytokines (IL-1β, IL-2, IL-4, IL-6, MCP-1, MIP-1α, MIP-1β, and TNF-α) and human herpesvirus (HSV1, HSV2, EBV, CMV, VZV, HHV6, HHV7, and HHV8) in saliva samples taken from subjects with and without peri-implantitis." (PMID 30158834, 2018).
pericardial effusion (2 papers, 2021 to 2024). Fluid collection within the pericardial sac, usually due to inflammation. "Other events accounting for the pathogenesis of cancer treatment-related pericardial effusion (CTR-pericardial effusion) are pericardial and endomyocardial fibrosis (busulfan) and increased endothelial permeability (interleukin-2 and dasatinib)." (PMID 38365812, 2024). "However, no existing study has been conducted to investigate the role of IL-2 and DEX in pediatric cancer patients with malignant pleural effusion, ascetics, and pericardial effusion." (PMID 34872514, 2021).
peripheral nerve injury (2 papers, 2020). Injury to a peripheral nerve. "Similarly, in the case of peripheral nerve injury NK cells are sufficient for degeneration of axons after IL-2/anti-IL-2 antibody complex stimulation despite the simultaneous expansion of CD8+ T cells." (PMID 32153361, 2020). "The cytokines IL6, TNF, IL10, IL2, and IL4 are all immunomodulatory factors, among which TNF and IL-6 have been confirmed to be involved in the pathological process of peripheral nerve injury." (PMID 33299447, 2020).
prediabetes (2 papers, 2023). "The present finding showed that serum Interleukin IL-2, IL-1β, and IL-1α levels of all prediabetes patients were increased when compared with healthy control cases (P < 0.05)." (PMID 37457235, 2023). "In prediabetes cases levels of cytokines: IL-2, IL-1β, and IL-1α were observed to be significantly higher than control group." (PMID 37457235, 2023). "Our findings showed that IL-1α, IL-1β and IL-2 were significantly elevated in individuals with prediabetes when compared with normal controls." (PMID 37457235, 2023).
premalignant oral lesions (2 papers, 2014 to 2018). "The results showed a dependence on IL-23 signaling for the pro-inflammatory state of mice with oral lesions as levels of IL-2, IFN-γ, IL-6, IL-17 and TNF-α were elevated in wildtype mice with premalignant oral lesions, but not in IL-23R KO mice." (PMID 29664967, 2018). "Levels of IL-2 and IFN-γ were not increased in the peripheral blood of patients with either premalignant oral lesions or HNSCC, although levels of IL-6 and IL-17 were increased in the plasma of patients with premalignant oral lesions as compared to control patients." (PMID 25419481, 2014).
proliferative diabetic retinopathy (2 papers, 2020 to 2025). Advanced retinopathy due to diabetes mellitus characterized by the formation of new vessels in the retina. "In individuals with non-proliferative and proliferative diabetic retinopathy, IL-2 levels are unchanged or reduced in vitreous and aqueous fluids compared with individuals without retinopathy." (PMID 40133487, 2025).
Proteinuria (2 papers, 2014 to 2017). Increased levels of protein in the urine. "Proteinuria in our patients correlated with both urinary IL-2 and IL-8 that points to association of proteinuria with ongoing injury in the KAG." (PMID 29162160, 2017).
radiation fibrosis (2 papers, 2020 to 2023). "IL-2 synthesis by myofibroblasts (activated fibroblasts) was already reported to be increased in patients suffering from post-radiation fibrosis." (PMID 33047019, 2020).
rectal cancer (2 papers, 2020 to 2023). A primary or metastatic malignant neoplasm that affects the rectum. "Elevated prostaglandin E2 can inhibit the production and effects of some inflammatory factors, such as IL-2, thereby inhibiting T-cell-related tumor immunity mediated by IL-2, suppressing immunity to rectal cancer." (PMID 32232384, 2020). "‘s study in rectal cancer found that mice treated with RT+IL-2 had a higher percentage of CD4+T cells but a lower percentage of Tregs and MDSC in splenocytes, Administering IL-2 significantly improved the anti-tumour impact of RT." (PMID 38259489, 2023).
renal adenocarcinoma (2 papers, 2017 to 2020). "On the contrary, in a model of experimental metastasis of renal adenocarcinoma, the treatment with a combination of IFN-γ and IL-2 had the most powerful inhibitory effect on pulmonary metastasis." (PMID 33312693, 2020).
renal fibrosis (2 papers, 2012 to 2019). A final common manifestation of a wide variety of chronic kidney diseases characterized by glomerulosclerosis and tubulointerstitial fibrosis. "On the other hand, TGF-β suppresses the synthesis of proinflammatory molecules, such as IL-2, alleviates renal fibrosis, and prevents the IL-1β-dependent proliferation of activated T cells." (PMID 30881587, 2019).
retinal (2 papers, 2021 to 2025). "The perforin cytotoxic pathway appears to be lost in retinitis-susceptible mice with MAIDS but is restored by systemic IL-2 immunotherapy that results in renewed resistance to MCMV retinitis as seen in healthy mice." (PMID 34358000, 2021). "Our studies exploring cytokine immunotherapy with IL-2 or IL-12 encouraged additional investigations to learn more about the possible contributions of individual cytokines toward the pathophysiology of MAIDS-related MCMV retinitis." (PMID 34358000, 2021).
retinal detachment (2 papers, 2012 to 2013). An eye emergency condition which may lead to blindness if left untreated. "Most cytokines concentrations (IL-2, IL-6, IL-8, IL-10, IL-17, TNF-α, IFN-γ, VEGF) were not statistically significant different compared to the rhegmatogenous retinal detachment control group except IL-1β." (PMID 23049699, 2012).
retinoblastoma (2 papers, 2019 to 2020). A malignant tumor that originates in the nuclear layer of the retina. "Encounter with any of the 3 retinoblastoma cell lines induced IFNG and IL2 release from CD171-specific CAR-T cells but not mock-transduced T cells used as negative controls." (PMID 31500597, 2019).
scrub typhus (2 papers, 2012 to 2023). Scrub typhus is a rare dust mite-borne infectious disease caused by the Orientia tsutsugamushi bacterium and characterized clinically by an eruptive fever which is potentially serious. "The increase of apoptotic cell death in T cells observed in scrub typhus patients, however, may not solely be due to AICD since it has been shown that the serum IL-2 levels in scrub typhus patients do not change during the symptomatic period." (PMID 22905277, 2012). "We also observed increased polyfunctionality in T cells when compared to unstimulated controls and this consisted of the triple (IFN-γ+TNF+IL-2) and double (IFN-γ+TNF) positive CD4+ T cell but not CD8+ T cells during acute infection of patients with scrub typhus." (PMID 36961865, 2023).